ALK (ALK receptor tyrosine kinase)
Diseases named in the same sentence as ALK in open-access papers (continued):
Sharing a sentence is not in itself a finding about the gene and the disease.
anaplastic large cell lymphoma (continued). "Our group has previously found that anti-CD30 conjugated to a commercially available liposomal doxorubicin (Doxil®) was significantly more effective in treating ALK-positive anaplastic large cell lymphoma in a SCID mouse xenograft model." (PMID 30791634, 2019). "Another chromosomal translocation between the nucleophosmin (NPM) gene on chromosome 5q35 and ALK gene on 2p23 is expressed in 60%–70% of anaplastic large cell lymphoma (ALCLs)." (PMID 29304828, 2018). "Anaplastic lymphoma kinase (ALK), firstly identified as fused to nucleophosmin in an anaplastic large-cell lymphoma cell line, is normally expressed in the brain, small intestine, and testis." (PMID 29455670, 2018). "It has been reported that the CD26/ADA complex is selectively expressed on Hodgkin’s and ALK-positive anaplastic large cell lymphomas." (PMID 29497379, 2018). "ALK-positive anaplastic large-cell lymphoma (ALK+ALCL) is a distinct form of T-cell non-Hodgkin lymphoma recognized in the World Health Organization Classification of Hematopoietic Neoplasms." (PMID 29609590, 2018). "ALK alterations have been described in multiple human cancers, most frequently translocations resulting in ALK fusion proteins in anaplastic large cell lymphoma, inflammatory myofibroblastic tumors and non-small cell lung cancers." (PMID 29531804, 2018). "Patients with anaplastic lymphoma kinase (ALK)-positive anaplastic large cell lymphoma (ALCL) mount a humoral and cellular immune response against ALK." (PMID 29642597, 2018). "For instance, it was down-regulated in metastatic prostate cancer (PCa), myeloid leukemias, endocrine-sensitive BCa, lung cancer, ALK-positive anaplastic large cell lymphomas (ALCLs), oral squamous carcinoma (OSCC), glioblastoma." (PMID 29217524, 2018). "In NHL cases, 12 cases were confirmed mucosa associated lymphoid tissue B lymphoma type, 3 cases were confirmed diffuse large B-cell lymphoma, angioimmunoblastic T-cell lymphoma and ALK positive anaplastic large cell lymphoma were one case separately." (PMID 29530011, 2018). "Anaplastic Lymphoma Kinase (ALK)-positive Anaplastic Large Cell Lymphoma (ALCL), remains one of the most curable cancers in the paediatric setting; multi-agent chemotherapy cures approximately 65–90% of patients." (PMID 29601554, 2018). "Four monthes later, the patient accepted bronchoscopy biopsy once again for sustained fever, and was confirmed ALK positive anaplastic large cell lymphoma finally." (PMID 29530011, 2018). "The identical rearrangement/CDR3 sequence has also been detected in DEL, a cell line established from malignant histiocytosis but also been recognized as an ALK-positive anaplastic large-cell lymphoma cell line." (PMID 30285677, 2018). "In the case of ALK-rearranged anaplastic large cell lymphoma (ALCL), invasiveness and dissemination of the tumor cells are dependent on the interaction of Rac signals with the oncogenic kinase, NPM-ALK." (PMID 30558116, 2018). "ALK-fusion genes have been observed in anaplastic large cell lymphomas (ALCLs) as a nucleophosmin 1 (NPM1)-to-ALK fusion gene, and in lung adenocarcinomas (lung ADCs) as an EML4-to-ALK fusion gene." (PMID 29760954, 2018). "Cell lysates from SupM2, an ALK-positive anaplastic large cell lymphoma cell line known to have a high pSTAT3 expression, were used as the positive control." (PMID 29914181, 2018). "Anaplastic large-cell lymphomas carrying anaplastic lymphoma kinase (ALK) have a relatively good prognosis, however aggressive forms exist." (PMID 30619326, 2018). "Further investigation will be needed to more precisely define the utility of RaFISH with other kinds of ALK probes and other types of malignant cells (e.g., anaplastic large cell lymphoma and inflammatory myofibroblastic tumors)." (PMID 29118432, 2017). "Best known are ALK gene alterations in anaplastic large cell lymphoma, lung adenocarcinoma, inflammatory myofibroblastic tumor and neuroblastoma." (PMID 27844328, 2017).
anaplastic large cell lymphoma (continued). "Large lymphoma cells were evident in the pericardial effusion, and a review of the previous lymph node biopsies confirmed the existence of ALK-positive anaplastic large cell lymphoma and tuberculous lymphadenitis." (PMID 28490385, 2017). "Anaplastic large cell lymphoma expressing anaplastic lymphoma kinase (ALK+ ALCL) is a distinct subtype of non-Hodgkin lymphoma." (PMID 29035291, 2017). "Crizotinib, a small molecule competitive inhibitor of anaplastic lymphoma kinase (ALK), has also shown high cytoreductive antitumour activity in anaplastic large-cell lymphoma." (PMID 29179521, 2017). "The observed RU/RR dichotomy appears to be a widespread phenomenon, as we have made similar observations in a number of other cancer types, including ER+ breast cancer, esophageal cancer and ALK-positive anaplastic large cell lymphoma." (PMID 28427212, 2017). "Here, we report a case of 32-year-old male with ALK positive anaplastic large cell lymphoma at the junction of jejunum and ileum, and highlight the clinicopathological features and the differential diagnosis of this type lymphoma." (PMID 27612448, 2016). "In general, we reported a rare case of primary intestinal ALK positive large cell lymphoma and highlighted the clinicopathological features and differential diagnosis." (PMID 27612448, 2016). "Constitutive activation of β-catenin in anaplastic lymphoma kinase (ALK)-positive anaplastic large cell lymphoma elevates STAT3 expression and activation." (PMID 27036017, 2016). "A diagnosis as primary small intestinal ALK positive anaplastic large cell lymphoma was finally made." (PMID 27612448, 2016). "Anaplastic lymphoma kinase (ALK) is an orphan receptor tyrosine kinase originally identified as part of the nucleophosmin (NPM)-ALK fusion gene in anaplastic large-cell lymphomas having a translocation." (PMID 27598116, 2016). "After the final diagnosis as primary ALK positive anaplastic large cell lymphoma, the patient received CHOP chemotherapy and is alive till now without recurrence 5 months after jejunectomy and ileectomy." (PMID 27612448, 2016). "Primary anaplastic large cell lymphoma, ALK positive in small intestine is clinically rare ﻿and the clinical, radiological and pathological information are generally not ﻿availab﻿le﻿." (PMID 27612448, 2016). "LR DLBCLs were associated with duplications of DVL3, a member of the disheveled protein family which has been described to promote cell growth in ALK-positive anaplastic large cell lymphoma." (PMID 27276707, 2016). "ALK+ Anaplastic Large Cell Lymphomas (ALCL) represent a defined subset of Non-Hodgkin lymphomas (NHL) characterized by chromosomal rearrangements involving the Anaplastic Lymphoma Kinase (ALK)." (PMID 27662658, 2016). "An aberration in the ALK gene was reported first in patients with anaplastic large-cell lymphoma and inflammatory myofibroblastic tumors with an ALK translocation and ALK amplification, respectively." (PMID 25941796, 2015). "The first report detailing ALK rearrangements was described in patients who were diagnosed with anaplastic large cell lymphoma (ALCL)." (PMID 25910080, 2015). "ALK rearrangements resulting in an activated ALK fusion protein were first identified in 1994 with the observation of nucelophosmin (NPM1)-ALK in anaplastic large cell lymphoma." (PMID 26062823, 2015). "The ALK + ve form of anaplastic large cell lymphoma is usually treated with CHOP chemotherapy and long term survival rates of 70–86% are reported." (PMID 25605631, 2015). "NVP-BGT226 has also been shown to exert cytotoxic effects against other cancer cell types such as ALK-positive anaplastic large cell lymphoma and hepatocellular carcinoma and has entered Phase I/II clinical trials for breast cancer." (PMID 26405162, 2015).
anaplastic large cell lymphoma (continued). "As proof-of-principle, we applied hiBA-FISH to measure the number of chromosome breaks at the NPM1 and ALK gene loci and the frequency of the anaplastic large cell lymphoma-specific NPM1-ALK translocation upon irradiation." (PMID 26313373, 2015). "This feature has favored a neoplastic nature of these tumors, as clonal abnormalities of the ALK gene were first described in anaplastic large cell lymphoma (ALCL), which is a true neoplasia." (PMID 25767734, 2015). "This is epitomized in Anaplastic Large Cell Lymphomas (ALCL) carrying Anaplastic Lymphoma Kinase (ALK) fusions." (PMID 26501073, 2015). "We found that an ALK-derived peptide of 36 amino acids (P36) was cytotoxic for ALK-positive anaplastic large-cell lymphoma and neuroblastoma cell lines." (PMID 25950466, 2015). "Anaplastic large cell lymphoma (ALCL) is divided into two systemic diseases according to the expression of the anaplastic lymphoma kinase (ALK)." (PMID 25688981, 2015). "Of all the T cell malignancies arising later than T ALL in development, the ALK + ve anaplastic large cell lymphoma is the only one with a significant chemotherapy cure rate." (PMID 25605631, 2015). "Crizotinib, an ALK inhibitor, is another FDA-approved drug for treatment of ALK-positive anaplastic large-cell lymphoma." (PMID 26134389, 2015). "The “lymphoma” plots include anaplastic large cell lymphoma (ALK-positive), primary cutaneous anaplastic large cell lymphoma, classical Hodgkin lymphoma, angioimmunoblastic T-cell lymphoma (all underexpressed), and mantle cell lymphoma (overexpressed)." (PMID 26269600, 2015). "ALK gene fusion occurs in limited subsets of cancer such as NSCLC, anaplastic large cell lymphoma, and inflammatory myofibroblastic tumor, whereas ALK mutation and copy number gain were observed in a wide range of cancers." (PMID 25803816, 2015). "Anaplastic Lymphoma Kinase-positive Anaplastic Large Cell Lymphomas (ALK+ ALCL) occur predominantly in children and young adults." (PMID 26338968, 2015). "ALK + ve large cell lymphoma arise from T cells that have undergone V[D]J recombination but have failed to produce a functional T cell receptor." (PMID 25605631, 2015). "A chimeric MYH9-Alk transcript formed by the fusion of MYH9 and ALK (anaplastic lymphoma kinase) was observed in anaplastic large cell lymphoma but its disease relevance is yet to be established." (PMID 25072053, 2014). "The anaplastic lymphoma kinase gene (ALK) is a member of the insulin receptor family and encodes a receptor tyrosine kinase that was originally identified in anaplastic large-cell lymphoma as a component of the fused protein NPM-ALK." (PMID 25527865, 2014). "GzB expression is also a hallmark of the non-Hodgkin lymphoma, anaplastic lymphoma kinase-positive, anaplastic large cell lymphoma (ALK+ ALCL)." (PMID 25168906, 2014). "IHC for ALK fusion protein expression has already been used for diagnosis of anaplastic large-cell lymphoma (ACLC) and inflammatory myofibroblastic tumor (IMT)." (PMID 24667320, 2014). "The earliest antibody developed was the ALK1 clone, which has primarily been used diagnostically in the detection of ALK-rearranged anaplastic large-cell lymphomas." (PMID 25188507, 2014). "In vitro, IL-9 was able to stimulate JAK3-dependent survival of ALK+ anaplastic large-cell lymphoma cells and protect thymic lymphoma cells from dexamethasone-induced apoptosis." (PMID 24722378, 2014). "The ALK gene was initially identified as a fusion partner of nucleophosmin in anaplastic large-cell lymphoma." (PMID 24475247, 2014). "The down-regulation of miR-15a/16-1 is also thought to be a molecular event underlying the pathogenesis of other types of lymphomas such as MCL and anaplastic lymphoma kinase (ALK)-positive anaplastic large cell lymphoma (ALCL)." (PMID 25232701, 2014).
anaplastic large cell lymphoma (continued). "ALK rearrangements leading to TPM3-ALK fusion have also been reported in anaplastic large cell lymphoma and papillary thyroid carcinoma, and result in a constitutive tyrosinase kinase activity, in this way causing tumor development." (PMID 25593912, 2014). "On the one hand, miR-29a and miR-29b are downregulated in mantle cell lymphoma, aggressive CLL samples (high ZAP-70 with unmutated IgVH), ALK-positive anaplastic large cell lymphomas (ALCL), MM, and AML." (PMID 23431463, 2013). "The ALK gene was initially characterized as a fusion partner of the NPM-ALK oncogene in anaplastic large cell lymphoma, and is now recognized as the active component in multiple fusion proteins in a variety of cancers." (PMID 23741400, 2013). "Anaplastic Lymphoma Kinase (ALK) was initially discovered as an oncogene in human anaplastic large cell lymphomas (ALCL), a subset of T-cell lymphomas." (PMID 23667670, 2013). "Based on the morphology, variable CD30, nuclear confined ALK expression, and leukaemic presentation in a young patient, a diagnosis of ALK-positive anaplastic large cell lymphoma with a small cell pattern was made." (PMID 24224107, 2013). "Before the identification of EML4-ALK fusion gene, Nucleophosmin-ALK (NPM-ALK) fusion gene was first identified in anaplastic large cell lymphoma." (PMID 23951022, 2013). "ALK fusion was originally described in anaplastic large-cell lymphoma as a chimeric protein NPM-ALK resulting from a translocation." (PMID 23289484, 2013). "Recently, we reported that C/EBPβ is overexpressed in anaplastic lymphoma kinase (ALK)+anaplastic large cell lymphoma (ALCL), and demonstrated that its expression is dependent on ALK kinase activity." (PMID 23741337, 2013). "Treatment with ALK inhibitors in vitro has been reported to lead to cell cycle arrest and apoptosis in anaplastic large-cell lymphoma, NSCLC, and neuroblastoma cells with any of the noted ALK rearrangements." (PMID 24156086, 2013). "C/EBPβ (CCAAT enhancer binding protein) is a transcription factor that plays a crucial role in survival and transformation of ALK+ anaplastic large cell lymphoma (ALCL)." (PMID 23741337, 2013). "In childhood, ALK-positive anaplastic large cell lymphoma is a major type of CD4- and TIA1-positive cytotoxic T/NK-cell lymphoma." (PMID 23302373, 2013). "The intracellular portion (containing the kinase domain) of ALK was firstly identified as part of the nucleophosmin (NPM)-ALK oncogenic fusion protein resulting from chromosomal translocation frequently associated with anaplastic large cell lymphoma (ALCL)." (PMID 22479414, 2012). "Mutations or translocations of the anaplastic lymphoma kinase (ALK) gene have been detected in several types of cancer, including anaplastic large-cell lymphoma, neuroblastoma, myofibroblastic tumor, and NSCLC." (PMID 25031955, 2012). "Anaplastic lymphoma kinase-positive, anaplastic large cell lymphoma (ALK+ ALCL) is a T cell lymphoma defined by the presence of chromosomal translocations involving the ALK tyrosine kinase gene." (PMID 22681779, 2012). "The anaplastic lymphoma kinase (ALK) gene was originally identified as part of a chromosomal translocation found in a subset of anaplastic large cell lymphomas." (PMID 22263108, 2012). "It is important to distinguish cases of ALK-positive anaplastic large cell lymphoma in analysis of T-cell lymphomas because of its exceptional good prognosis." (PMID 21188274, 2010). "Aberrant ALK activity has recently been shown to be present in anaplastic large cell lymphoma, as well as in solid tumors, including NSCLC." (PMID 20624322, 2010). "T-cell lymphomas are a heterogeneous group of diseases but are uniformly aggressive and respond poorly to our conventional chemotherapy, with the notable exception of ALK-positive anaplastic large cell lymphoma." (PMID 21188274, 2010).
anaplastic large cell lymphoma (continued). "Except for ALK positive anaplastic large cell lymphoma, T-cell lymphoma responds to conventional chemotherapy unfavourably, and most patients carry poor prognosis.In recent years, efforts have been made to improve the outcome of T-cell lymphoma patients." (PMID 21188274, 2010). "Conventional CHOP-like chemotherapy yields poor response in T-cell lymphomas excluding ALK-positive anaplastic large cell lymphoma." (PMID 21188274, 2010). "When patients with ALK-positive anaplastic large cell lymphomas are excluded, the overall and event-free survival at 12 years dropped to 21% and 18%, respectively." (PMID 21188274, 2010). "All of them carry poor prognosis with the notable exception of anaplastic lymphoma kinase (ALK)- positive anaplastic large cell lymphoma." (PMID 21188274, 2010). "Anaplastic lymphoma kinase-positive diffuse large B-cell lymphoma (ALK-DLBCL) is a rare lymphoma with several clinicopathological differences from ALK-positive anaplastic large cell lymphoma (ALCL)." (PMID 19250532, 2009). "DnStat3 also inhibits Stat3 signaling in ALK-positive anaplastic large cell lymphoma by suppression of several Bcl-2 family genes." (PMID 18939995, 2008). "This is consistent with previous study that targeting Stat3 signaling with dnStat3 suppresses cell-cycle-related genes, including cyclin-D1, in ALK-positive anaplastic large cell lymphoma." (PMID 18939995, 2008). "Amplification of ALK, a gene with transforming activity in anaplastic large cell lymphoma was also seen." (PMID 17327916, 2007). "ALK encodes a tyrosine kinase receptor and was first identified as a component of the NPM-ALK fusion gene in anaplastic large cell lymphoma." (PMID 17327916, 2007). "The third ALK– anaplastic large-cell lymphoma case was a rare presentation of T-cell anaplastic large-cell lymphoma arising in the soft tissue around a breast implant in a 49-year-old female." (PMID 16623775, 2006). "There is a trend for ALK– anaplastic large-cell lymphoma to have gains of chromosome 1q (46% versus 17%, Fisher's P = 0.0577)." (PMID 16623775, 2006). "The remainder of this section will discuss the case against placing ALK– anaplastic large-cell lymphoma back into the category peripheral T-cell lymphoma unspecified." (PMID 16623775, 2006). "The degree of genetic instability varied between ALK– and ALK+ anaplastic large-cell lymphoma and peripheral T-cell lymphoma unspecified, with the greatest in the latter." (PMID 16623775, 2006). "Virtually all (82–100%) systemic anaplastic large-cell lymphomas, including ALK+ and ALK– cases, and 41–100% of PC anaplastic large-cell lymphomas express clusterin, a ubiquitous glycoprotein encoded by a gene on chromosome 8p21." (PMID 16623775, 2006). "Another Workshop case of primary cutaneous anaplastic large-cell lymphoma was ALK– but expressed EMA." (PMID 16623775, 2006). "However, NGS testing revealed a TRAF1::ALK translocation, which led to a revised diagnosis of stage IV ALK-positive anaplastic large cell lymphoma (ALCL), a curable cancer." (PMID 40161372, 2025). "Moreover, the expression of TWIST1 has not yet been studied in B-cell or T-cell acute lymphoblastic leukemia (B-All/T-ALL), but it is significantly expressed in ALK+ anaplastic large cell lymphoma (ALCL) and cutaneous T-cell lymphoma (CTCL)." (PMID 39941895, 2025). "While first-line therapy predominantly involves CHOP (cyclophosphamide, doxorubicin, vincristine, and prednisone) regimens, the prognosis for the majority of peripheral T-cell lymphoma (PTCL) subtypes remains unfavorable, except for ALK-positive anaplastic large cell lymphoma." (PMID 41394820, 2025). "For the present case, inflammatory spindle cell lesions of the cavum abdominals should be dominantly considered as differential diagnosis, where IMT and anaplastic large cell lymphoma (ALCL) would be much more likely to be identified as ALK-positive tumors, especially IMT (including its subtypes)." (PMID 40224190, 2025).